PCBP2 (poly(rC) binding protein 2)
Diseases named in the same sentence as PCBP2 in open-access papers (continued):
Sharing a sentence is not in itself a finding about the gene and the disease.
infection (continued). "Cells were fixed at 3 hours post-infection and then labeled with a PCBP2 antibody." (PMID 21779168, 2011). "Therefore we suggest that PCBP2 is a cellular protein that may be usurped by rabies virus during infection to afford differential regulation of expression of its glycoprotein mRNA." (PMID 22438951, 2012). "Upon infection, H5N1 generates miR-HA-3p, which suppresses poly(rC)-binding protein 2 (PCBP2) to produce high levels of proinflammatory cytokines and results in high mortality." (PMID 33255826, 2020). "Indeed, PCBP2 was shown to negatively regulate innate immune signalling: PCBP2 triggers mitochondrial antiviral signalling protein (MAVS) for degradation and, upon infection with VSV and sendai virus, knockdown of PBCP2 increases MAVS-mediated signalling." (PMID 37606964, 2023). "Investigation on the regulation of PCBP1 and PCBP2 transcripts after the infection (0–2 h) showed no significant alteration by quantitative PCR analysis in splenocytes and by semiquantitative RT–PCR in J774 cells (0–8 h)." (PMID 36309090, 2022). "PCBP2 binds domains II and III rather than the unique structure of DHAV-1, suggesting that PCBP2 may play the same role during infections with other type IV IRES viruses." (PMID 39300570, 2024). "However, on day 4 post-infection, lungs of mice infected with H5N1 virus had a significantly lower level of PCBP2 protein compared to that of mice infected with H5N1 virus but at the same time treated with antagomir-HA-3p or mice infected with mutant H5N1 virus." (PMID 29327729, 2018). "Indeed, a recent report demonstrated that three HRV serotypes do not induce the cleavage of PCBP2 or PTBP1 during infection of a human lung cell line, suggesting alternative mechanisms must be used under theses experimental conditions." (PMID 26150805, 2015). "However, whether DHAV-1 utilizes the host protein PCBP2 for viral translation and replication during infection has not been reported." (PMID 39300570, 2024).
neurodegenerative disease (4 papers, 2017 to 2025). A disorder of the central nervous system characterized by gradual and progressive loss of neural tissue and neurologic function. "Both PCBP2 and TDP-43 are known to co-localize within pathological aggregates in neurodegenerative disease." (PMID 39282431, 2024).
GI tumors (1 paper, 2024). "In addition, some transcription factors, including HDGF, NCL, PCBP1, and PCBP2, were also found to be largely modified by lysine lactylation in all four types of GI tumors, and further confirming the regulation of Kla in gene expression." (PMID 39018247, 2024).
heart disease (1 paper, 2021). "An additional illustration of a prospective treatment strategy on the subject of heart disease is Poly(C)-binding protein 2 (PCBP2) which was shown to be reduced in the diseased heart in humans as well as in hypertrophied hearts in mice." (PMID 33923168, 2021).
PCBP2 also shares sentences with these, for which no sentence is quoted: frontotemporal dementia (4 papers); proteinopathies (2); semantic dementia (2); Alzheimer disease (1); amyotrophic lateral sclerosis (1); cardiac hypertrophy (1); chronic obstructive pulmonary disease (1); Cognitive impairment (1); colon adenocarcinoma (1); Glucose intolerance (1); idiopathic interstitial pneumonia (1); myocardial infarction (1); Obesity (1); pneumonia (1); renal carcinoma (1); respiratory diseases (1); tauopathy (1); triple-negative breast carcinoma (1); ZIKV infection (1).